CSF1 (colony stimulating factor 1)
Diseases named in the same sentence as CSF1 in open-access papers (continued):
Sharing a sentence is not in itself a finding about the gene and the disease.
tumor (continued). "In summary, our findings demonstrated that HOMER3-AS1 drives HCC progression via modulating the behaviors of both tumor cells and macrophages, which are dependent on the activation of HOMER3/Wnt/β-catenin axis and CSF-1, respectively." (PMID 34815380, 2021). "When exposed to IL4, IL5, IL10, IL13, CSF1, TFGB1, and prostaglandin E2 (PGE2), it transitions from a pro-inflammatory state to an anti-inflammatory and pro-tumor state, that is, to an M2-like state." (PMID 34447750, 2021). "Downregulation of circCDC45 or CSF-1 blocked GBM cell proliferation, invasion and migration as well as tumor growth in vivo." (PMID 34627193, 2021). "Tumor-derived CSF1 induces the expression of granulin in macrophages, which impedes the infiltration of cytotoxic CD8+ T cells at the site of the tumor lesion, resulting in resistance to immune checkpoint therapy." (PMID 34248982, 2021). "In the TME with low oxygen concentration, tumor cells can recruit TAMs by secreting more chemokines such as CCL2, CCL5, or CSF1." (PMID 34717710, 2021). "In colorectal cancer, senescent tumor cells inhibit CD8+ T cell infiltration by secreting a high concentration of CXCL12 and enhanced M2 macrophage differentiation by CSF1." (PMID 33643790, 2021). "Studies had shown that the dual inhibition of FGF and CSF1 or VEGF signals was expected to enhance the antitumor effect by targeting immune escape and angiogenesis in the tumor microenvironment." (PMID 35155566, 2021). "As CSF-1 receptor is only expressed on GAMs, tumour cells can be presumed to secrete CSF-1 to regulate GAM behaviour and thus influence tumour biology." (PMID 33803414, 2021). "EGCG treatment decreased the levels of colony stimulating factor 1 (CSF-1) and CCL-2 within the tumor and hence reduced the infiltration of TAM-like M2 macrophages in the 4T1-bearing mice." (PMID 34948368, 2021). "In vivo studies in tumor-bearing CCR2 knock-out mice and CSF-1 depleted tumor graft models have shown reduced TAM density, inhibition of protumor cytokine expression, and prolonged survival in these mice." (PMID 34439281, 2021). "PC-derived chemokine CXCL12 (SDF-1) can trigger the EGF/CSF-1 paracrine invasion loop to mediate the co-migration of TAM and tumor cells, after binding to its receptor CXCR4 on both TAMs and tumor cells (process ➁)." (PMID 34179005, 2021). "The CSF1/CSF1R axis is positively correlated with VEGF-A expression, which contributes to tumor angiogenesis." (PMID 33406733, 2021). "CSF1/CSF1R signaling increases angiogenesis, cancer growth, metastases, invasion, CD8+ T cell suppression, tumor macrophage recruitment, and resistance to therapy." (PMID 33747948, 2021). "CSF-1, CCL2, 3, 14, and IL-4 are common tumor-derived factors driving the recruitment, proliferation, and M2-polarization of MPs." (PMID 33418996, 2021). "Increased levels of CCL2, CSF1, and VEGF-A are correlated with macrophage accumulation at the tumor site in a wide spectrum of human cancers, including those of breast, prostate, ovarian and lung." (PMID 34771482, 2021). "The small molecule BLZ-945 specifically inhibits CSF-1R phosphorylation and blocks CSF-1-mediated signal transduction in TAMs, leading to apoptosis and improving CTC infiltration in the tumor 96,97." (PMID 34158855, 2021). "The M-MDSC is attracted to tumor sites by CCL2, CCL5, and CSF1 and PMN-MDSC was attracted by CXCL1, CXCL5, CXCL6, CXCL8, and CXCL12." (PMID 34858479, 2021). "Upon chemical and irradiation exposure, surviving cancer cells produce pro-tumor cytokines as IL-17, stromal cell-derived factor-1 (SDF-1), CCL2, and colony-stimulating factor 1 (CSF-1), which limit the therapeutic benefits." (PMID 33800829, 2021). "In several solid tumors, macrophages are recruited to the tumor site through a gradient of chemotactic molecules, such as CCL2 (also known as MCP-1), colony stimulating factor 1 (CSF-1, also known as M-CSF) or several CXCL chemokines." (PMID 34572939, 2021).
tumor (continued). "The infiltration of TAMs to hypoxic tumor areas is due to various stimuli including Sema3A/Nrp1 signaling, VEGF, migratory stimulating factors such as colony-stimulating factor 1 (CSF1), CCL2, CCL5 as well as upregulation of TGFβ and M-CSFR." (PMID 34202979, 2021). "CSF-1 is a monocyte attractant as well as a macrophage survival and polarization factor that drives TAM differentiation towards an immunosuppressive, tumor promoting ‘M2-like’ phenotype." (PMID 33731849, 2021). "A recent study showed that the high expression of Snail1 in mesenchymal tumor cell induces the expression of several cytokines (CD73, CSF1, SPP1), which collectively expedites the assembly of tumor immunosuppressive microenvironments." (PMID 34917071, 2021). "MDSCs are recruited to tumor sites through GM-CSF; monocyte chemoattractant protein 1 (MCP1); CXCL1, 2, 5, and 12; IL-8; CSF1; prokineticin 2 (Prok2); CCL2; S100A8/9; and other factors derived from the TME47,61,62." (PMID 34403220, 2021). "For example, the blockade of CSF1/CSF1R pathway and CCL2/CCR2 axis prevented TAM recruitment and improved anti-tumor immunity." (PMID 34575463, 2021). "The central role of stroma‐derived mediators is exemplified by (i) WNT4 stimulating tumour cell adhesion and migration, (ii) activation of pro‐inflammatory signaling by extracellular HSP70 and (iii) CSF1 inducing macrophage proliferation." (PMID 34841720, 2021). "Inhibition of CCL2/CCR2 or CSF1/CSF1R signaling pathway can reduce the intratumoral infiltration of M2-TAM and inhibit tumor growth and metastasis." (PMID 34583750, 2021). "This study provides insight into the crosstalk between TWIST1 and CSF1 in metastatic OSCC and supports TWIST1-mediated macrophage activation to promote tumor invasion." (PMID 33466385, 2021). "During tumor progression TAMs often switch to an anti-inflammatory M2 status after exposure to cytokines within the TME including: IL-4, M-CSF/CSF1, IL-10, IL-33, IL-21, and TGF-β." (PMID 35127700, 2021). "Colorectal cancer-derived TNFα facilitates tumor growth and TAM recruitment, in turn, inducing TAM-mediated secretion of autocrine CSF1." (PMID 33406733, 2021). "Therefore, the involvement of CSF-1 during tumour initiation might be tissue-specific." (PMID 32325966, 2020). "For example, dual targeting of suppressive myeloid populations by inhibiting CSF-1/CSF-1R signalling and activation of APCs with CD40 agonists conferred superior anti-tumour efficacy and increased survival compared with monotherapy." (PMID 31973030, 2020). "Tumor cells-macrophage co-culture increases expression of IL10, IL12, IL6, TNF, CCL5, CCL22, and CSF1 in macrophages, thereby inducing M2-like polarization." (PMID 32219066, 2020). "CSF-1 plays a particularly important role in TAM as it contributes not only to TAM differentiation, but also invasion into tumor tissue." (PMID 31963413, 2020). "The process of migration occurs through chemotaxis and is conditioned by tumor-released ligands, such as chemokine (C-C motif) ligand 2 (CCL2), CCL5 and colony stimulating factor 1 (CSF-1)." (PMID 32488850, 2020). "The described recruitment and polarization are promoted by the tumor and immune cell secreted cytokines, growth factors and metabolites such as VEGF, colony stimulating factor-1 (CSF-1) and chemokine CCL2." (PMID 33167307, 2020). "Immunohistochemical staining of macrophages (CD68+ cells), p-BRD4 and CSF1 showed that macrophages were present in nearly all these implantation tumors, and p-BRD4 and CSF1 were expressed mostly in tumor cells." (PMID 32286255, 2020). "Because IL4, IL13, IL10, and CSF-1 are stimuli in M2 differentiation as reported in previous studies 6, 20, we performed qRT-PCR in FOXO1(+) and FOXO1(-) tumor cells to detect the expression of these genes." (PMID 33052231, 2020).
tumor (continued). "The majority of macrophages present in the tumor microenvironment are recruited from bone marrow-derived monocytes through the CC chemokine 2 (CCL2/CCR2) and colony stimulating factor 1 (CSF-1/CSF-1R) signaling pathways." (PMID 32326073, 2020). "This paracrine interaction between CSF-1-secreting tumor cells and EGF-secreting macrophages drives the migration of tumor cells and the macrophages toward blood vessels." (PMID 32182935, 2020). "Tumor infiltrated Treg cells and M2 macrophages significantly correlate with the tumor suppressive system in STAD as they produce cytokines such as transforming growth factor beta 1 (TGF-β1), interleukin-10 (IL-10), and colony stimulating factor 1 (CSF1)." (PMID 32408477, 2020). "Since the early steps of tumorigenesis, cancer and stromal cells increase the number of TAMs in the tumor, by producing chemokines and growth factors (e.g., CCL2 and CSF1)." (PMID 33050070, 2020). "Macropinocytosis normally occurs in response to stimulation by growth factors such as the macrophage colony-stimulating factor-1 (CSF-1), the epidermal growth factor (EGF) and the platelet-derived growth factor or tumor-promoting factors." (PMID 31976201, 2020). "As for humoral factors, VEGF, macrophage migration inhibitory factor (MIF), IL-6, IL-4/13, IL-10, TGFβ, POSTN, colony-stimulating factor-1 (CSF-1), CCL2, CXCL12, and COX-2/PGE2 directly or indirectly regulate the immunosuppressive tumor microenvironment." (PMID 32707672, 2020). "Macrophages are mainly recruited from the bone marrow via colony-stimulating factor 1 (CSF-1) and monocyte chemotactic protein 1 (MCP-1) signaling, which are particularly driven by the hypoxic conditions in the tumor tissue." (PMID 33042814, 2020). "In GBM, TAMs are recruited to the tumour site through various mediators, including CCL2, CX3CL1, CSF-1, GM-CSF and osteopontin released by neoplastic cells." (PMID 31973030, 2020). "Monocytes are recruited from the circulation and differentiate into macrophages within the TME where stromal and tumor cells provide chemokines and growth factors mainly CCL2, CSF1, CCL18, CCL20, CXCL12, and VEGF-A." (PMID 31256327, 2020). "circASAP1 sponged miR-326 and miR-532-5p, increasing their targets MAPK1 and colony stimulating factor 1 (CSF1), respectively, that contributed to promote tumor cell proliferation and invasion as well as macrophage infiltration in the tumor." (PMID 32429062, 2020). "Western blotting, qRT-PCR, and enzyme-linked immunosorbent assay were used to evaluate chemokine ligand 20 (CCL20) and colony stimulating factor 1 (CSF-1) expression in FOXO1(+) and FOXO1(-) tumor cells." (PMID 33052231, 2020). "In particular, mediators like CSF-1, CCL2 and vascular endothelial growth factor (VEGF) promote TAM accumulation in the tumor microenvironment." (PMID 32708142, 2020). "CSF-1R is a tyrosine kinase receptor that when bound with its ligand CSF-1 promotes the differentiation and expansion of myeloid cells into MDSC and TAMs in addition to promoting their migration to tumours." (PMID 32121014, 2020). "On the other hand, RT can induce the recruitment of macrophages into the tumor tissue by stimulation of CCL2, CSF1 production and promote the tumor progression." (PMID 33062602, 2020). "On the other hand, CSF1 overexpression strongly mitigated the tumor inhibitory effects of NHWD-870 on A2780 tumors, as measured by net tumor weight, ascitic fluid volume and tumor implantation." (PMID 32286255, 2020). "This principally occurs through potent upregulation of chemoattractants in the tumour microenvironment (TME) for circulating monocytes, including colony stimulating factor 1 (CSF-1) and monocyte chemoattractant protein-1 (MCP-1)." (PMID 33081206, 2020). "CSF-1 drives TAM differentiation towards an immunosuppressive, tumor-promoting, M2-like phenotype, while IFNγ or GM-CSF promote classically activated M1 macrophages." (PMID 31554173, 2019).
tumor (continued). "Peripheral microglia are attracted and recruited inside the tumor core by the secreted factors released from the tumor cells like CCL2, CSF1, or EGF." (PMID 31824268, 2019). "Further, it also acts as a chemo-attractant for macrophages in the TME, and these tumor-guided macrophages are themselves a good source of VEGF, MMPs, and M-CSF/CSF1." (PMID 31769418, 2019). "Tumor-derived GM-CSF and MIP2 account for MDSC, CSF1 and BAG31 for TAM recruitment and expansion, GM-CSF being also provided by tumor-associated mesenchymal cells." (PMID 31921628, 2019). "Specifically, TAMs can directly help tumor cell migration via a paracrine loop between macrophages and tumor cells that involves the secretion of EGF family ligands from macrophages and CSF1 from tumor cells." (PMID 31998650, 2019). "These MAMs allow the extravasation of mouse tumor cells by secreting the chemokine ligand CCL3 and CSF-1 that facilitates metastatic seeding of breast cancer cells in the lung and potentially VCAM-1 that transmits survival signals to these tumor cells." (PMID 30832375, 2019). "The tumor cell lines K1, BCPAP, HTC/C3, and FR081–2, and the immortalized cell line Nthy induced differentiation of macrophages and expressed CSF-1." (PMID 31113465, 2019). "In conclusion, a positive feedback is established between tumour cells, TEMs, and TAMs: tumour cells recruit TEMs by expressing CXCL12, receptor to CXCR4, which is located on the TEM surface, and TAMs through CSF-1 and TGFβ." (PMID 31554160, 2019). "Colony stimulating factor 1 (CSF1) stimulates M1 to M2 polarization, and then boosts tumor proliferation and survival." (PMID 31695804, 2019). "These pathways were all connected to tumor growth, and the PI3K/Akt signaling pathway (eight involved genes: CCND2, CDKN1B, CSF1, EFNA3, FGFR2, FGFR3, IL2RB, and ITGA9) ranked first among upregulated pathways (Enrichment Score = 3.159187)." (PMID 30755239, 2019). "During tumor development, cancer cells secrete chemokines such as CCL2, CCL5, CXCL12, and colony stimulating factor 1 (CSF1) to recruit immune cells towards the tumor site." (PMID 31766635, 2019). "Given that anti-CSF1R blocks both CSF1 and IL34 binding and MC38 tumor cells express both these cytokines, our studies reveal that TAM homeostasis is primarily dependent on CSF1." (PMID 31552020, 2019). "Inflammatory monocytes are rapidly recruited at sites of tumor growth, following specific signaling by chemokines (e.g., CCL2), but also CSF-1, cytokines, or complement components (C5a)." (PMID 31878087, 2019). "MDSCs are attracted to tumor sites in response to various cytokines (CCL2, CCL5, and CSF1 for M-MDSCs, and CXCL1, CXCL5, CXCL6, CXCL8, and CXCL12 for PMN-MDSCs)." (PMID 31412566, 2019). "Tumor cells release factors, such as vascular endothelial growth factor (VEGF), colony stimulating factor 1 (CSF1), and platelet-derived growth factor (PDGF), that aid in the recruitment of macrophages to tumors." (PMID 30925923, 2019). "Hypoxia, colony stimulating factor 1 (CSF-1), TGF- β, IL-4 and IL-13 are able to enhance the switch of TAM from M1 to M2 phenotype, thus changing the M1/M2 ratio while tumor progression." (PMID 30680411, 2019). "It is well-demonstrated that CSF1 and CX3CL1 control the recruitment of TAMs into tumor microenvironment." (PMID 30237497, 2018). "By RNA profiling, Western blot and luciferase reporter assay, we further observed that miR-125b directly regulated tumor cell-derived chemokine CSF1 and CX3CL1, which are known to control the recruitment of TAMs to tumor sites." (PMID 30237497, 2018). "In breast cancer, hypoxia upregulates the expression of CSF-1 via mediation of CCL5/CCR5, which induces the recruitment of TAMs and MDSCs from the peripheral blood to tumor sites and converts them to the suppressive phenotype." (PMID 30619286, 2018). "Irradiation to murine tumours generated from colorectal (MC38) and pancreatic (KPC) cell lines induced colony‐stimulating factor 1 (CSF‐1)." (PMID 30442705, 2018).
tumor (continued). "YAP activates expression of cytokines and chemokines such as C-C motif chemokine ligand 2 (CCL2) and colony stimulating factor 1 (CSF1), thus recruiting macrophages to tumor-initiating cells to protect them from immunosurveillance." (PMID 30453531, 2018). "Their influx and positioning in the tumour is mediated by chemokines (e.g., CCL2), growth factors (e.g., CSF1) and complement components." (PMID 29422500, 2018). "The transient induction of tumour cell CSF‐1 gene expression was reflected in a similar pattern of protein secretion in vivo, which may be explained by the short period of cell viability following radiation before mitotic catastrophe or apoptosis results in tumour cell death." (PMID 30442705, 2018). "TAMs can be polarized into tumor-promoting phenotype with immune modulatory effects by tumor-derived instructive signals within the TME, such as CSF-1, lactate and PGE2." (PMID 30563569, 2018). "M2 TAMs secrete colony-stimulating factor 1 (CSF-1) that has been found in high levels in malignant EOC, and contributes to tumor growth, invasion, and metastasis." (PMID 30042343, 2018). "Collectively, these data indicated that CSF-1 is sufficient to induce RAE-1δ on macrophages, and that CSF-1 is necessary for macrophage RAE-1δ induction by B16 and KP tumor cell supernatants in vitro." (PMID 29757143, 2018). "Similar to MDSCs, TAMs and TANs are recruited to tumor sites by tumor-derived chemokines and growth factors, including CCL2/MCP-1, CXCL1/Gro-a, CCL7/MCP-3, CCL5/RANTES, CXCL8/IL-8, VEGF, PDGF, and M-CSF/CSF-1." (PMID 29735917, 2018). "CSF-1R expression is restricted, at the tumor site, to macrophages, allowing the regulation of infiltration and function of TAMS by CSF-1." (PMID 28567162, 2017). "Colony-stimulating factor 1/CSF1-R signaling drives the recruitment and the differentiation of TAMs toward a M2 phenotype in tumor." (PMID 28769933, 2017). "These include blocking macrophages by inhibiting CSF-1/CSF1R signaling, as well as disrupting cytokines/chemokines that recruit and polarize macrophages to a pro-tumor phenotype." (PMID 28881599, 2017). "CSF-1 also stimulates macrophages to release EGF, which promotes tumor cell proliferation and migration." (PMID 28955335, 2017). "We next measured whole tumor RNA levels of the chemokine receptors CXCR2 and CSF1R as well as the cognate chemokines for these receptors, CXCL1/CXCL2 and CSF1, respectively." (PMID 28915554, 2017). "In line with this idea of vascular network functionality improvement, tumor hypoxia highlighted by Glut1‐positive tumor cells area was reduced in response to TMZ and this effect was exacerbated following TMZ plus anti‐CSF1 co‐treatment (Fig EV5C and D)." (PMID 29038312, 2017). "CSF1/CSF1 receptor (CSF1R) signaling is critical for the generation of monocyte progenitors in bone marrow and TAM polarization in tumor tissues." (PMID 28241846, 2017). "CSF1R activation leads to the recruitment of CSF1R-expressing macrophages that constitute a large part of the tumor mass in dt-GCT, thus making this pathway an ideal therapeutic target for compounds interfering with the CSF1/CSF1R-signaling axis." (PMID 28716061, 2017). "We cover fundamental molecular players in the tumor microenvironment including extra- (CCL2, CSF-1, CXCL12, IL-4, IL-13, semaphorins, WNT5A, and WNT7B) and intracellular signals." (PMID 28197019, 2017). "Experimental inhibition of macrophage infiltration into the primary tumor delayed the angiogenic switch, which could be restored by the genetic restoration of the infiltrating macrophage population through transgenic overexpression of macrophage-colony-stimulating factor (CSF-1)." (PMID 29037250, 2017). "Colony-stimulating factor 1 (CSF1)/CSF1 receptor (CSF1R) signaling is critical for the generation of monocyte progenitors in bone marrow and TAM polarization in tumor tissues." (PMID 28804638, 2017).